IL26 (interleukin 26)
Diseases named in the same sentence as IL26 in open-access papers (continued):
Sharing a sentence is not in itself a finding about the gene and the disease.
allergic contact dermatitis (1 paper, 2025). An inflammatory skin condition caused by an immune response to direct contact between the skin and an allergen. "In patients with allergic contact dermatitis (ACD), IL-26 expression is significantly upregulated in the skin (with or without lesions), as well as in peripheral blood mononuclear cells (PBMCs)." (PMID 41516201, 2025).
astrocytoma (1 paper, 2025). "The influence of CAPE on the secretion of cytokines (IL-8, IL-10, IL-26), metalloproteinases (MMP-1, -2, -3), and pentraxin-3 (PTX3) was assessed in CCF-STTG1 astrocytoma cells stimulated with LPS and/or IFN-α under normoxic and hypoxic conditions." (PMID 41515435, 2025).
autoimmune gastritis (1 paper, 2022). Inflammation of the body fundic mucosa of the stomach. "We investigated the serum levels of different cytokines, such as IL-19, IL-20, IL-26, IL-28A and IL-29 in patients with pernicious anemia and autoimmune gastritis or iron deficient anemia without autoimmune gastritis." (PMID 35479078, 2022). "We compared serum levels of IL-19, IL-20, IL-26, IL-28A and IL-29 in 43 patients with PA and autoimmune gastritis, in 20 patients with IDA and no autoimmune gastritis, and in 47 HC." (PMID 35479078, 2022).
Autoimmunity (1 paper, 2024). The occurrence of an immune reaction against the organism's own cells or tissues. "Type III IFN and cytokines IL-10, IL-22, and IL-26 are ligands for this receptor, thereby linking the genetic overdosage in trisomy 21 with autoimmunity and autoinflammation in DS." (PMID 39457216, 2024).
bacteremia (1 paper, 2019). "Furthermore, septic patients with bacteremia had lower circulating IL-26 levels when compared to non-bacteremic patients." (PMID 31464651, 2019).
bipolar disorder (1 paper, 2022). A disorder of the brain that causes unusual shifts in mood, energy, activity levels and the ability to carry out day-to-day tasks. "As in the two prior independent datasets, there was no enrichment for trans- or cis-risk of psychiatric disorders at epigenetically activated sites in myeloid cells, either stimulated or unstimulated, with the exception of enrichment of bipolar disorder risk in IL26-stimulated macrophages." (PMID 36243721, 2022).
bronchiolitis obliterans syndrome (1 paper, 2022). A lung disorder that is mainly associated with chronic allograft dysfunction after lung transplantation and that is characterized by inflammation and fibrosis of bronchiolar walls that reduce the diameter of the bronchioles and result in progressive and irreversible airflow obstruction. "Furthermore, a recently published study in a murine model of mice transplanted with human umbilical cord blood of cGVHD showed that IL26+CD26+CD4 T cell infiltration has the potential to play an important role in obliterative bronchiolitis." (PMID 35501858, 2022).
cutaneous sarcoidosis (1 paper, 2020). "Here, we focused on cutaneous sarcoidosis and also report a significant increase in IL26 gene expression whereas the gene expressions of IL22 and IL17A were not affected." (PMID 33057074, 2020).
eczema (1 paper, 2024). "Both IL-26 and IL-17 A were also increased systemically in dog allergen-sensitized subjects with eczema compared with control subjects." (PMID 38622712, 2024).
elephantiasis (1 paper, 2014). Enlargement of an area of the body due to obstruction within the lymphatic system and the resulting accumulation of lymph. "Increased IL-26 expression, in contrast, appears to be associated with the pathological consequences of infection (e.g. lymphedema and/or elephantiasis)." (PMID 24699268, 2014).
esophageal diseases (1 paper, 2018). "Because IL-26 is only expressed in humans and not in mice, the lack of animal models may in part explain why IL-26 has not been to our knowledge studied yet in contexts of esophageal diseases." (PMID 29967613, 2018).
experimental autoimmune encephalomyelitis (1 paper, 2022). An autoimmune demyelinating disease of the central nervous system that is produced experimentally in animals by the injection of homogenized brain or spinal cord in Freund's adjuvant. "Although IL-26 is not produced in mice or rats, mice express a functional IL-26 receptor, and administration of human IL-26 has been reported to affect the severity of experimental autoimmune encephalomyelitis." (PMID 36311716, 2022).
fulminant viral hepatitis (1 paper, 2023). Fulminant viral hepatitis is a rapid and severe impairment of liver functions (acute liver failure) with hepatic encephalopathy developing less than 8 weeks after the onset of jaundice, secondary to viral hepatitis mainly due to HBV, but also to HAV. "Further studies are required to compare the clinical manifestations and cellular responses to IL-10, IL-22, IL-26, and IFN-λ1 of patients with IL-10RB deficiency, with or without fulminant viral hepatitis." (PMID 36308662, 2023).
gastric tumor (1 paper, 2025). "Finally, functional validation through CCK-8 proliferation assays, wound Healing assays, and transwell assays conclusively demonstrated the tumor-promoting effects of IL-17A and IL-26 on gastric tumor cells." (PMID 40452847, 2025).
glioblastoma (1 paper, 2025). The most malignant astrocytic tumor (WHO grade IV). "In summary, PCA demonstrated that under normoxic conditions, CAPE was associated with a shift in the global biochemical profile of glioblastoma cells in the absence of LPS stimulation, primarily through suppression of IL-26." (PMID 41515435, 2025).
graft versus host disease (1 paper, 2022). An immune system disorder that occurs after allogeneic hematopoietic stem cell transplant and is a reaction of donor immune cells against host tissues. "Furthermore, Ohnuma and colleagues outlined that CD26+ CD4+ T cells constitute a significant source of IL-26 in a mouse model of graft-versus-host disease (GVHD)." (PMID 36294822, 2022).
HCMV infection (1 paper, 2013). "The inhibition of the HCMV infection of IL-26-treated fibroblasts of about 50% was further quantified by flow cytometry in comparison to the control protein IL-2." (PMID 23875025, 2013). "In comparison to VSV, higher IL-26 concentrations (at least 5 μg/ml) were necessary for effects on HCMV infection and the IL-26 pre-incubation of the HCMV supernatant or of the target cells showed similar results." (PMID 23875025, 2013). "In contrast to VSV, the IL-26 effects on HCMV infection needed higher IL-26 concentrations and were comparable if the virions or the cells were pre-treated with the cytokine (data not shown)." (PMID 23875025, 2013). "The neutralization of the IL-26 inhibition of HCMV infection was only achieved partially probably since high IL-26 concentrations were used." (PMID 23875025, 2013). "In summary, IL-26-dependent effects on VSV and HCMV infection of appropriate target cells can be neutralized with anti-IL-26 polyclonal serum in a dose-dependent manner." (PMID 23875025, 2013). "The IL-26-mediated enhancement of VSV infection, the inhibition of HCMV infection, and the unchanged HSV-1 infection were further confirmed and quantified by flow cytometry and by virus titration." (PMID 23875025, 2013). "The rabbit serum was used for neutralization of the IL-26 effects, in order to demonstrate the IL-26-specificity on VSV and HCMV infection." (PMID 23875025, 2013). "Whereas VSV infection was strongly enhanced by IL-26, HCMV infection was inhibited, and HSV-1 infection was not influenced." (PMID 23875025, 2013). "This is consistent with the highest IL-26-dependent inhibition of HCMV infection at low MOI (data not shown)." (PMID 23875025, 2013). "A moderate inhibition of HCMV infection with rather high IL-26 concentrations was observed, regardless of whether cells or virus were treated." (PMID 23875025, 2013).
hepatitis C (1 paper, 2018). "Furthermore, previous studies have revealed that IL-26 upregulates tumor necrosis factor (TNF)-related apoptosis-inducing ligand (TRAIL) expression in human NK cells, which induces the elimination of hepatitis C-infected hepatocytes." (PMID 29698503, 2018).
HIV-1 infection (1 paper, 2017). The type species of lentivirus and the etiologic agent of acquired immunodeficiency syndrome (AIDS). "HIV-1 infection of microbe-exposed LP CD4+ T cells stimulated 3.4-fold higher levels of IL26, a Th17-derived cytokine that has antibacterial properties, and 3.0-fold higher levels of the IL23R, which acts as the receptor of IL23 and helps maintain Th17 cell function." (PMID 28241075, 2017).
Hypoxemia (1 paper, 2025). An abnormally low level of blood oxygen. "Hypoxemia among RSV-positive individuals could also be categorized based on IL-26, G-CSF, and IFNβ levels." (PMID 41488910, 2025).
inflammatory bone diseases (1 paper, 2025). "In summary, our findings decipher the crucial role of IL-26 in the regulation of osteoblast cells and bone homeostasis, suggesting that IL-26 could be a potential therapeutic target for inflammatory bone diseases such as OA." (PMID 40093804, 2025).
influenza (1 paper, 2025). An acute viral infection of the respiratory tract, occurring in isolated cases, in epidemics, or in pandemics; it is caused by serologically different strains of viruses (influenzaviruses) designated A, B, and C, has a 3-day incubation period, and usually lasts for 3 to 10 days. "Prediction of influenza cases was moderately better, but required more cytokines, including IL-26, Il-27p28, IFNλ2, and LIGHT." (PMID 41488910, 2025).
intestinal cancer (1 paper, 2025). "Given that bacterial infections in the gut are known to cause DNA damage and contribute to IBD and intestinal cancer, we examined whether IL-26 plays a role during gut bacterial infections." (PMID 41125850, 2025).
Iron deficiency anemia (1 paper, 2022). "Luminex assay results for IL-19, IL-20, IL-26, IL-28A and IL-29 levels in sera of HC, Healthy controls; IDA, Iron deficiency anemia patients; PA, Pernicious anemia patients." (PMID 35479078, 2022).
leiomyoma (1 paper, 2025). A well-circumscribed benign smooth muscle neoplasm characterized by the presence of spindle cells with cigar-shaped nuclei, interlacing fascicles, and a whorled pattern. "This study evaluated the expression of STAT-3 and IL-26, two early components of the relevant signaling pathways in leiomyoma tissue in uterine fibroid development; some limitations should be emphasized." (PMID 40943781, 2025). "In contrast, we observed an increase in the number of cells showing high IL-26 positivity in smooth muscle cells and fibroblasts forming leiomyomas in the uterine tissue in the case group." (PMID 40943781, 2025). "In accordance with the light microscopic evaluation, patients in the leiomyoma group had significantly higher IL-26 h-scores than those in the control group (3.46 ± 2.21vs." (PMID 40943781, 2025). "This study aimed to immunohistochemically detect STAT-3 and IL-26 expression in leiomyoma tissues and determine whether these signaling pathways play a role in leiomyoma pathophysiology." (PMID 40943781, 2025). "Therefore, analyzing IL-26 expression in the myometrium and fibroids may be important for determining the role of cytokines in the development of leiomyomas." (PMID 40943781, 2025). "Leiomyoma sections showed strong staining for STAT-3 and IL-26 compared with that in the normal myometrium." (PMID 40943781, 2025). "Sections from the myometrium of the control group and the leiomyoma tissue of the case group were subjected to immunohistochemical staining for STAT-3 and IL-26." (PMID 40943781, 2025). "However, the lack of specific studies on the expression and effects of IL-26 in uterine fibroids makes it difficult to clarify the role of this cytokine in fibroid pathogenesis." (PMID 40943781, 2025).
leprosy (1 paper, 2020). Leprosy is a chronic infectious disease affecting primarily the skin and peripheral nervous system. "This supports previous studies which found that the autophagy inhibiting cytokine IL-10 is predominant in multibacillary leprosy compared to high levels of IL-26, IFN-γ, and TNF-α, autophagy inducing cytokines, found during paucibacillary tuberculoid leprosy." (PMID 33519771, 2020).
leukemia (1 paper, 2020). A malignant (clonal) hematologic disorder, involving hematopoietic stem cells and characterized by the presence of primitive or atypical myeloid or lymphoid cells in the bone marrow and the blood. "NK-22, a human NK cell subset, secretes leukemia inhibitory factors (LIFs), IL-22, and IL-26." (PMID 32290250, 2020).
lymphedema (1 paper, 2014). Excess fluid collection in tissues, causing swelling. "Moreover, the frequency of CD4+ and CD8+ T cells expressing IL-26 was significantly increased following filarial antigen stimulation in filarial lymphedema individuals." (PMID 24699268, 2014).
mastitis (1 paper, 2020). Inflammation of breast tissue during lactation or postpartum due to an obstructed duct or infection. "Five genes (EPOR, IL9, IFNL3, CCL26, and IL26) that were involved in this pathway might serve as potential molecular markers for breeding programs that enhance resistance to S. aureus infection and mastitis." (PMID 32944235, 2020).
Mycobacterium infection (1 paper, 2025). Infections with bacteria of the genus Mycobacterium. "Accordingly, IL-26 has been characterized in blood monocytes in the context of Mycobacterium tuberculosis infection by microarrays, RT-qPCR, and ELISA, confirming the constitutive expression of IL-26 and its downregulation as a response to Mycobacterium infection." (PMID 41516201, 2025).
neurosyphilis (1 paper, 2023). Infection of the brain or spinal cord by Treponema pallidum. "Meanwhile, the increased levels of CXCL9, CXCL7, CCL24, IL-17, IL-26, and migration inhibitory factor (MIF) of macrophages in the CSF of neurosyphilis patients suggested their role as promising differential diagnostic tools for neurosyphilis." (PMID 38105236, 2023).
obstructive lung disease (1 paper, 2024). "Notably, we found that patients with comorbid obstructive lung disease were 4.270 times more likely to have an IL-26 measurement above the LLOD than patients without this comorbidity." (PMID 39430762, 2024).
palmoplantar pustulosis (1 paper, 2025). A rare skin disease characterized by chronic eruption of sterile pustules on an erythematous and desquamative background, affecting the palms and soles, sometimes also the lateral aspects of hands and feet. "A unique subset of Th17 cells with regulatory phenotype drives inflammation in palmoplantar pustulosis by producing IL-17F and IL-26 and interacting with inflammatory keratinocytes." (PMID 40985896, 2025).
pancreatic ductal adenocarcinoma (1 paper, 2025). An infiltrating adenocarcinoma that arises from the epithelial cells of the pancreas. "In pancreatic ductal adenocarcinoma cells, IL-26 engagement of its receptor complex induces phosphorylation of STAT3, MAPK1, and MAPK3, promoting tumor aggressiveness." (PMID 41516201, 2025).
periodontitis (1 paper, 2019). An acute or chronic inflammatory process that affects the tissues that surround and support the teeth. "Levels of sCD30/TNFRSF8, IFN-α2, IL-19, IL-26, MMP-1, gp130/sIL-6Rß, and sTNF-R1 were significantly higher in serum or GCF, and April/TNFSF13 was significantly higher in serum and saliva samples in moderate/severe periodontitis." (PMID 31072030, 2019). "In GCF samples, significantly (p < 0.05) higher levels of IFN-α2, IL-19, IL-26, MMP-1 and sTNF-R1 were observed in RA patients with moderate/severe periodontitis compared to corresponding RA subjects with no/mild periodontitis." (PMID 31072030, 2019). "In the present study, the levels of sCD30 (TNFRSF8), sTNF-R1, gp130 (sIL-6Rß), IL-19, IL-26 and MMP-1 were increased in serum, saliva or GCF samples from subjects with moderate/severe periodontitis as compared to no/mild disease." (PMID 31072030, 2019).
pulmonary diseases (1 paper, 2022). "Moreover, NLRP3-derived cytokines (e.g., IL-1β, IL-18) appear to be the main inducers of a cytokine cascade (involving IL-23, IL-17, IL-26, IL-6, IL-13, and IL-5) that is responsible for the development of pulmonary diseases in morbidly obese subjects." (PMID 35806353, 2022).
pulmonary tuberculosis (1 paper, 2024). A bacterial infection that affects the lungs and is caused by Mycobacterium tuberculosis. "To bridge this knowledge gap, we quantified IL-26 levels in plasma and IL-26 mRNA expressions in PBMCs from 25 patients diagnosed with active pulmonary tuberculosis and 29 healthy controls using the ELISA and RT-PCR methods, respectively." (PMID 39431054, 2024). "Interestingly, our findings demonstrated significantly elevated IL-26 mRNA expression in PBMCs from pulmonary TB patients compared to healthy individuals." (PMID 39431054, 2024).
renal failure (1 paper, 2019). "Serum concentrations of ALT and AST, markers for hepatocellular injury; LDH, a marker for general cellular injury; and creatinine, a marker for renal failure, were significantly increased in septic mice treated with recombinant human IL-26 at 24 h after CLP." (PMID 31464651, 2019).
skin infection (1 paper, 2024). An inflammatory process affecting the skin, caused by bacteria, viruses, parasites, or fungi. "IL-17A and to a lesser degree, IL-22 have been linked to protection in mouse models of skin infection yet IL-26 remains quite understudied, likely due to its absence in the mouse genome and to the difficulty to reveal it by intracellular cytokine staining." (PMID 39981298, 2024).
staphylococcal infection (1 paper, 2021). An infection caused by Staphylococcus. "Notwithstanding, and despite having higher levels of the antimicrobial chemokine Il-26 in plasma, HS patients appeared to be more susceptible to staphylococcal infections." (PMID 34696185, 2021).
tuberculoid leprosy (1 paper, 2023). A principal or polar form of leprosy in which the skin lesions are few and are sharply demarcated. "This supports previous studies which found that the xenophagy inhibiting IL-10 cytokine is predominant in multibacillary leprosy (MB) compared to high levels of IL-26, IFN-γ, and TNF-α (xenophagy-inducing cytokines) found during paucibacillary tuberculoid leprosy (PB)." (PMID 38133338, 2023).
tuberculous pleurisy (1 paper, 2024). "To date, only one study has investigated the role of IL-26 in tuberculous pleurisy, finding significantly higher expression of IL-26 in CD4+T cells, NK cells, and NKT cells, but not CD8+T cells, in TPE compared to blood samples." (PMID 39003443, 2024). "It is widely accepted that IL-10, IL-22 and IL-26 inhibit the pathological progression of tuberculous pleurisy by suppressing inflammatory responses while promoting local immune responses." (PMID 39003443, 2024).
type II diabetes (1 paper, 2012). "As IL-26 induces the secretion of active IL-1-beta (without affecting IL-1RA and IL-10 production), its involvement in sterile auto-inflammatory disorders (such as type II diabetes) should be investigated." (PMID 23055831, 2012).